ALDH18A1 (aldehyde dehydrogenase 18 family member A1)
Diseases named in the same sentence as ALDH18A1 in open-access papers (continued):
Sharing a sentence is not in itself a finding about the gene and the disease.
brain disorder (1 paper, 2021). A disease affecting the brain or part of the brain. "The network revealed that the majority of the disorders are linked with DYNC1H1 (k = 91), LMNA (k = 86), FMR1 (k = 74), DCTN1 (k = 57), and ALDH18A1 (k = 54) genes and showed interactions with multiple brain disorders." (PMID 34832615, 2021). "Interestingly, out of five key SG genes that showed a high number of associations with brain disorders, three genes, namely LMNA (k = 14), DCTN1 (k = 8), and ALDH18A1 (k = 4), also play important roles in disorders having a major impact on lungs and respiratory ability of the patients." (PMID 34832615, 2021).
neurodevelopmental disorder (1 paper, 2025). A behavioral and cognitive disorder with onset during the developmental period that involves impaired or aberrant development of intellectual, motor, or social functions. "Among the additional variants related to neurodevelopmental disorders identified by Trio-WES, ALDH18A1 (NM_002860.4): c.683C>T (p.P228L) and ASH1L (NM_018489.3): c.6238G>A (p.V2080I) were de novo and paternally inherited, respectively, but did not fulfill the criteria for co-segregation." (PMID 40574801, 2025).
ALDH18A1 also shares sentences with these, for which no sentence is quoted: Ataxia (3 papers); autosomal dominant cutis laxa-3 (3); Burkitt lymphoma (3); cataract (3); connective tissue disease (3); Argininemia (2); developmental delay (2); hyperprolinemia type 2 (2); malaria (2); metabolic disorders (2); anemia (1); autoimmune disease (1); autosomal dominant spastic paraplegia (1); autosomal recessive complex spastic paraplegia type 9B (1); Autosomal Recessive Spastic Paraplegia (1); Cerebellar atrophy (1); cervical cancer (1); Cognitive impairment (1); colitis (1); colon cancer (1); COVID-19 (1); cryptosporidiosis (1); diabetes (1); Dysarthria (1); epilepsy (1); gastroesophageal reflux (1); gastroparesis (1); Hepatic steatosis (1); hiatal hernia (1); hyperopia (1).
A further 27 diseases each share a sentence with ALDH18A1 in 1 paper.